COMT (catechol-O-methyltransferase)
Diseases named in the same sentence as COMT in open-access papers (continued):
Sharing a sentence is not in itself a finding about the gene and the disease.
breast cancer (continued). "A cohort study was conducted to examine the role of genetic polymorphisms in three estrogen metabolizing enzymes (COMT, CYP1A1, CYP1B1) and the two estrogen receptors (ESR1, ESR2) in the progression of benign breast disease (BBD) to breast cancer." (PMID 16808847, 2006). "We used a case-only design to examine the potential interaction between methylation status – as measured by COMT genotype – and active or passive smoking status among women with breast cancer." (PMID 16417624, 2006). "With greater control over potential misclassification errors and a large case-only population, we found evidence to support an interaction between COMT genotype and tobacco smoke exposure in breast cancer etiology." (PMID 16417624, 2006). "Among women carrying at least one low-activity COMT allele, those consuming tea displayed a significantly decreased risk of developing breast cancer (OR 0.48 (95% CI 0.29–0.77)) with respect to non-tea drinkers." (PMID 32085420, 2020). "In the Chinese population, the catechol-O-methyltransferase genotype did not present any modifying effect on the association between tea consumption and breast cancer risk." (PMID 28845434, 2017). "The high adduct ratios in women at high risk for breast cancer and the association of SNPs in CYP1B1 and COMT with increased odds of ovarian cancer provide particularly strong evidence for a critical role of estrogen-DNA adducts in the etiology of these cancers." (PMID 30854528, 2017). "In addition, studies showed that quercetin can downregulate the expression of catechol-O-methyltransferase (COMT) and inhibited its activity by estrogen receptor, and it can reduce the influence of estrogen metabolites on breast cancer." (PMID 25530789, 2014). "The exact relationship between genetic polymorphisms of COMT Val158Met and susceptibility to breast cancer has not been entirely established." (PMID 23039364, 2012). "Catechol-O-methyltransferase (COMT) is one of the most important enzymes involved in estrogen metabolism and its functional genetic polymorphisms may be associated with breast cancer (BC) risk." (PMID 23039364, 2012). "We did not observe a positive relationship between COMT Val108/158Met polymorphism and breast cancer risk either overall or among subgroups of women defined by ethnicity, menopausal status or sources of the control population." (PMID 23039364, 2012). "Those SNPs located in ERα, ERβ, HSD17B1, COMT and CYP1B1 genes may also be associated to mammographic density (MD), which is a strong and independent risk factor for breast cancer." (PMID 21092186, 2010). "Analysis of the independent contribution of COMT polymorphism has also shown a statistically significant association between the COMTHigh (ValVal) genotypes and increased breast cancer risk in Ontario but not in Finland sample." (PMID 18194538, 2008). "Genetically, our findings suggests that the individuals inheriting the combinations of high activity COMT and CCND1 alleles have relatively higher breast cancer risk probably due to simultaneous reduction in estrogen metabolism, and increase in cell proliferation." (PMID 18194538, 2008). "CCND1.COMT interaction in breast cancer cases from Ontario and Finland populations." (PMID 18194538, 2008). "A recent meta-analysis concluded that there was no major association between COMT polymorphisms and breast cancer risk." (PMID 16417624, 2006). "We identified 502 cases of invasive incident breast cancer and characterized COMT genotype." (PMID 16417624, 2006). "However, the correlation between the chemotherapy-related PM impairment and the COMT polymorphisms in breast cancer patients with the disparate status of HER2 had not yet been illustrated." (PMID 35211407, 2022). "Furthermore, the COMT (rs165599, rs737865) polymorphisms were correlated to the risk of TBPM decline scores and possibly be a potential genetic identifying for increasing risk of CRCI in breast cancer patients with disparate status of HER2." (PMID 35211407, 2022).
breast cancer (continued). "Nonetheless, the present data are in alignment with several previous studies showing a relationship between COMT and self-reported fatigue in other pathologies (e.g., breast cancer) and healthy participants, supporting the idea that the COMT gene may influence fatigue perception." (PMID 33909692, 2021). "Given the broad function of COMT and its implication in a wide spectrum of clinical conditions, a thorough understanding of how expression of this gene is regulated may be therapeutically transformative in diseases as diverse as alcoholism and breast cancer." (PMID 24460628, 2014). "A large meta-analysis conducted by Xue Qin confirmed that COMT Val108/158Met polymorphism may not be associated with breast cancer risk." (PMID 23635316, 2013). "Our meta-analysis results suggest that the COMT Val158Met polymorphism may not contribute to breast cancer susceptibility." (PMID 23039364, 2012). "In conclusion, this meta-analysis suggests that the COMT Val158Met polymorphism may not be associated with breast cancer risk." (PMID 23039364, 2012). "Two found that the elevated breast cancer risk for women with low COMT activity was greater among non-smokers than smokers and two found no meaningful difference in risk of breast cancer by COMT activity across smoking groups." (PMID 16417624, 2006). "In this study, the A/A genotype carriers of COMT (rs165599) and G/G genotype carriers of COMT (rs737865) had higher scores on TBPM after chemotherapy and were genetic risks for CRCI in breast cancer with disparate expression of HER2." (PMID 35211407, 2022). "The present study investigated the novel biological activities of NDGA in relation to COMT and the effects of COMT inhibition by NDGA on 4-OHE2-induced cyto- and genotoxicity in MCF-7 human breast cancer cells." (PMID 33916785, 2021). "On the other hand, genetic variations in canine COMT gene (which encodes catechol-O-methyltransferase, an enzyme involved in estrogens metabolism through inactivation of carcinogenic catechol estrogens) has not been proved to influence susceptibility to canine mammary tumors." (PMID 31506083, 2019). "We previously reported that 4-OHE2 and COMT inhibitors can induce phosphorylated histone H2AX, a marker of DNA damage, in human MCF-7 breast cancer cells." (PMID 28163803, 2017). "In human breast cancer cells, 4-OHEN was observed to induce DNA damage and apoptosis, and was toxic towards MCF-10A cells in the presence of COMT inhibitor." (PMID 22140478, 2011). "Similarly, in human breast cancer cells (MCF-7), 4-OHE2 treatment and inhibition of catechol-O-methyltransferase (COMT), the enzyme responsible for the breakdown of catechol estrogens into methoxyestradiol, induced γH2Ax expression in response to DNA damage." (PMID 40869324, 2025). "The consequences indicated that the heterogeneity of CRCI may be regulated by COMT (rs165599 and rs737865), which may affect the CRCI in breast cancer with disparate status of HER2." (PMID 35211407, 2022). "We then aimed at assessing the association between these symptoms and clinical/genetic factors that have never been previously explored in breast cancer patients (expect for COMT rs4680) and we highlighted some new interesting findings." (PMID 34330229, 2021). "Accumulation of 4-OHE2, due to decreased COMT activity, is hypothesized to confer increased risk for breast cancer suggesting that a polymorphism in COMT is associated with increased risk of breast cancer, however, some studies suggest that a COMT polymorphism is not linked with breast cancer." (PMID 32498358, 2020). "However, no studies have explored the role of COMT SNPs in the development of chronic shoulder pain following breast cancer surgery with a mixed ancestry background." (PMID 36672750, 2022).
breast cancer (continued). "The breast tissue from women with breast cancer also demonstrated greater expression of the estrogen-activating enzymes CYP19 and CYP1B1, compared to women without breast cancer, who exhibited greater expression of the estrogen-protective enzymes COMT and NQO137." (PMID 30854528, 2017). "Further evidence of imbalance in estrogen homeostasis derives from the greater expression of estrogen-protective enzymes, COMT and NQO1, in women without breast cancer and greater expression of estrogen-activating enzymes, CYP19 and CYP1B1, in breast tissue of women with breast cancer." (PMID 26979321, 2016).
Cognitive impairment (46 papers, 2009 to 2026). Abnormal cognition is characterized by deficits in thinking, reasoning, or remembering. "Increased COMT methylation has been associated with malnutrition and impaired cognition, consistent in the direction of our adult discovery cohort." (PMID 38342906, 2024). "Catechol-O-methyl transferase (COMT) gene variants are involved in different neuropsychiatric disorders and cognitive impairments, associated with altered dopamine function." (PMID 37510262, 2023). "Genetic variants of COMT have been associated with the risk of cognitive impairment in cannabis users." (PMID 37185752, 2023). "Previous findings indicated that polymorphism in gene catechol-O-methyltransferase (COMT) had been linked to chemotherapy-related cognitive impairment (CRCI)." (PMID 35211407, 2022). "We initially examined the association of cognitive deficits in SGA-treated subjects stratified by their COMT rs5993883 genotypes (linear regression 1)." (PMID 27039372, 2016). "COMT Val carriers (both Val-Val and Val-Met) are considered relatively at risk for specific cognitive deficits with aging and possibly MCI." (PMID 25249975, 2014). "Second, the COMT G variant (including Val-Val and Val-Met) has been identified as a risk factor for cognitive deficits with normal aging, given the association with the degradation of catecholamine neurotransmitters (such as dopamine)." (PMID 25249975, 2014). "Specifically, COMT is an enzyme that degrades catecholamines in the synaptic cleft and SNPs within the coding sequence of this gene are associated with cognitive deficits." (PMID 22384243, 2012). "Therefore, COMT gene and its polymorphisms have been studied in different neuropsychiatric disorders and cognitive impairments, associated with altered dopamine function." (PMID 37510262, 2023). "Conversely, analysis of the AKT1 and COMT genotypes revealed that over half (> 55%) of the participants had gene variants that significantly increased their risk of potentially developing psychotic symptoms and/or cognitive impairment." (PMID 33526106, 2020). "Several studies suggest that cognitive impairments in working memory and executive functions are linked to polymorphisms in the COMT gene and this association might be the mechanism explaining G × E interactions." (PMID 28822116, 2018). "Also linked to cognitive deficits associated with SGA-treatment are catechol-O-methyltransferase (COMT) gene variants." (PMID 27039372, 2016). "Discussion: Both chronicity and emergence of objectively classified early cognitive impairment may be genetically heterogeneous phenomena, with influences from a panel of both normal cognitive aging (COMT) and AD-related (APOE) polymorphisms." (PMID 25249975, 2014). "With the purpose of examining the influence of COMT, a gene involved in estrogen metabolism, as a genetic risk factor for cognitive impairment, we conducted a study of a sample of patients with mild cognitive impairment (MCI), Alzheimer's disease (AD) and a control group." (PMID 19793392, 2009). "(2012) proposed a synergistic interaction between the COMT rs4680 G/G genotype and APOE‐ε4, increasing susceptibility to cognitive impairments." (PMID 41476008, 2026). "According to the GSEA phenotype analysis, APOE, BDNF, CACNA1A, COMT and UCHL1 were identified as the main genes associated with cognitive impairment (FDR q-value < 0.05)." (PMID 41301762, 2025). "COMT inhibition has been proposed as a therapeutic strategy for combating cognitive impairment, particularly disorders of cognitive control." (PMID 32508604, 2020). "What is more interesting regarding the current findings is the potential role of the COMT gene as a factor contributing to the cognitive impairment in fibromyalgia." (PMID 32752289, 2020).
Cognitive impairment (continued). "SNPs in both catechol-O-methyltransferase (COMT) and ankyrin repeat and kinase domain-containing 1 (ANKK1) have been associated with a variety of cognitive impairments after predominantly mTBI, but this association is less clear in sTBI." (PMID 31105646, 2019). "Consistent with our predictions, a higher genetic risk score significantly predicted a higher risk of having cognitive impairment (OR = 3.824, P = .013, and 95% C.I. = 1.333, 10.973) when controlling individual polymorphisms in BDNF, COMT, and APOE." (PMID 26366299, 2015). "In summary, we found that a cumulative genetic risk score across three genes related to cognition, brain function, and risk for dementia (BDNF, COMT, and APOE) significantly predicted late-life cognitive impairment." (PMID 26366299, 2015). "Chemotherapy induced cognitive impairment may also be associated with genetic vulnerability factors: the genes coding apolipoprotein E (APOE) and catechol-O-methyltransferase (COMT) have been suggested to be variables." (PMID 29113386, 2017). "Their presence may be correlated with cognitive impairment; however, the relationship between regional WMH volume and catechol-O-methyltransferase (COMT) Val158Met polymorphism in healthy populations remains unclear." (PMID 24551149, 2014). "Accordingly, prospective studies might elucidate not only the role of COMT genotypes in AD, but also in the evolution of cognitive impairment from the early stages." (PMID 19793392, 2009). "Genetic polymorphisms in select genes, including APOE (apolipoprotein E), COMT (Catechol-O-Methyltransferase), MDR1 (multi-drug resistance 1), BDNF (brain derived neurotrophic factor), and GST (glutathione-S-transferase), have been associated with vulnerability to cognitive impairment." (PMID 33731765, 2021). "We created a genetic risk score to represent the accumulation of risk genotypes of polymorphisms in BDNF, COMT, and APOE to test whether the risk score predicted the presence of late-life cognitive impairment above and beyond that of each individual gene polymorphism." (PMID 26366299, 2015). "Interestingly, either haploinsufficiency of Nrg1 or overexpression of Nrg1 in mice can result in some types of cognitive deficits, which implies a possible U-shaped relationship between Nrg1 expression and cognitive function, which has been reported for the COMT gene." (PMID 24782733, 2014). "These kinds of patients should be managed through a review of dopaminergic drugs, avoiding dopamine agonists and Catechol-O-methyltransferase (COMT) inhibitors, dealing with cognitive impairment, and using more easily atypical antipsychotics." (PMID 39766432, 2024). "Although different genetic factors involving dopamine availability (i.e, the COMT gene) have been associated with the more severe presentation of key symptoms in fibromyalgia, scientific evidence regarding the influence of COMT genotypes on cognitive impairment in these patients is still lacking." (PMID 32752289, 2020). "Interestingly, individuals with increased COMT activity appear to have stronger responses to THC administration in terms of acute psychotic effects and cognitive impairments." (PMID 23936144, 2013). "At early stages of the disease, the combination of treatments decreasing DA levels in the striatum and COMT inhibitors increasing DA levels in the PFC, might prevent the exacerbation of cognitive deficits, or even improve cognitive ability in Val/Val HD gene carriers." (PMID 27657697, 2016).
bipolar disorder (38 papers, 2005 to 2025). A disorder of the brain that causes unusual shifts in mood, energy, activity levels and the ability to carry out day-to-day tasks. "A study of patients with bipolar disorder and their relatives found a significant interaction between the COMT rs4680 Val allele, childhood trauma, and dissociative symptoms." (PMID 35627228, 2022). "In several independent studies, D-amino acid oxidase activator (DAOA) and Catechol-O-methyltransferase (COMT) have been found to be associated with bipolar disorder." (PMID 23861766, 2013). "For example, it has been known for over two decades that in bipolar disorder, variants in genes related to neurotransmitter systems, such as Catechol-O-methyltransferase, serotonin transporter, and tryptophan hydroxylase gene polymorphisms have been implicated." (PMID 40282331, 2025). "The negative effects of antipsychotic medication on cognitive functioning in patients with bipolar disorder, may be partly moderated by COMT Val108/158 Met Val allele load." (PMID 23421957, 2013). "Moreover, in patients with bipolar or manic disorders, the presence of COMT V158M polymorphism could lead to choosing different therapeutic options rather than APDs, like antiepileptics or lithium salts." (PMID 34679357, 2021). "Patients with bipolar disorder displayed a negative modulating effect of COMT Val108/158Met Val allele load on the effects of antipsychotics on two-year cognitive functioning." (PMID 23421957, 2013). "Our finding that cognitive manic symptoms in patients with bipolar disorder was associated with genetic variants in the DAOA and COMT genes, in both case-case and case-control analyses, supports that impaired cognitive functioning in general might be associated with the DAOA and COMT genes." (PMID 23861766, 2013). "In a second sample; inpatients with bipolar disorder, we explored the interaction between COMT and proline on negative-symptom change (using the BPRS-negative-symptom subscale)." (PMID 27622935, 2016). "Proline may also interact with COMT (encoded by COMT at 22q11.2) genotype in modifying negative symptoms in both SCZ and bipolar disorder and in modifying startle reactivity in 22q11.2DS." (PMID 41235103, 2025). "To support our primary finding of an interaction on negative symptoms, and because negative symptoms are present across psychiatric disorders, in an exploratory study, we also assessed the relationship between proline and COMT on negative symptoms in bipolar disorder." (PMID 27622935, 2016). "The negative effects of antipsychotics on cognitive functioning in bipolar disorder may be moderated by the COMT Val 108/158 Met genotype, with a negative effect of Val allele load." (PMID 23421957, 2013).